CNTN1 (contactin 1)
Diseases named in the same sentence as CNTN1 in open-access papers (continued):
Sharing a sentence is not in itself a finding about the gene and the disease.
cancer (30 papers, 2009 to 2025). A tumor composed of atypical neoplastic, often pleomorphic cells that invade other tissues. "Unsurprisingly, increased CNTN1 expression was found to have functional associations in promoting cancer cell progression and metastasis." (PMID 32752094, 2020). "It is also reported that CNTN1 knockdown influences genes involved in tumorigenesis although its overexpression affects genes associated with cancer, immunologic disorders, and inflammation." (PMID 33194679, 2020). "Positioned at the crossroad of pathways associated with cancer invasion and metastasis, CNTN1 represents a promising target for cancer therapy." (PMID 32752094, 2020). "Our initial screen revealed a significant association between elevated CNTN1 and reduced overall survival (OS) in all cancer types." (PMID 32752094, 2020). "Despite being primarily studied for its roles in the human nervous system, CNTN1 has been implicated in several signaling pathways altered in cancer." (PMID 32752094, 2020). "Adhesion is an essential process regulating tumorigenesis and cancer progression; in this regard, it is important to revisit the evidence supporting CNTN1-associated oncogenic functions." (PMID 32752094, 2020). "The upregulation of CNTN1, its association with worse clinical features, and its functionality in promoting cancer progression suggest CNTN1 being a potential target of cancer therapy." (PMID 32752094, 2020). "In different cancer types, CNTN1 is positively associated with lymphatic invasion, metastasis, late TNM stage, and a short overall survival time although its role in proliferation remains controversial." (PMID 33194679, 2020). "The involvement of CNTN1 in cancer formation and progression is supported by its common amplification in cancers and the association of this upregulation with the clinical features of cancers." (PMID 32752094, 2020). "Abnormalities in CNTN1 expression associate with cancer progression and poor prognosis." (PMID 32752094, 2020). "While these analyses support a positive association between high CNTN1 expression and poor OS in cancers, this association might be cancer-type specific at least at the level of mRNA; high CNTN1 expression displays a reverse association with poor OS in LGG." (PMID 32752094, 2020). "Despite accumulating evidence supporting a role of CNTN-1 in cancer metastasis, the underlying mechanisms responsible for this process remains unclear." (PMID 23724143, 2013). "Considering CNTN1′s role in facilitating cell invasion and metastasis, it may be of interest to generate CNTN1-relevant conditional knock-in transgenic models to further explore the causal link between CNTN1 with cancer progression and metastasis." (PMID 32752094, 2020). "Our previous study found that contactin 1, which is an adhesion molecule involved in carcinogenesis and cancer progression, accounts for drug resistance in SCLC by inducing Akt signaling pathway accompanied by epithelial–mesenchymal transition progression." (PMID 41460862, 2025). "The CNTN1 gene is mapped to human chromosome 12q11-q12, which is close to a breakpoint region of cancers." (PMID 33194679, 2020). "Among the 17 selected differentially expressed proteins, we selected the 2 with the lowest and highest fold-change (cancer/control), along with gelsolin and contactin-1, which are related to TC, for further validation." (PMID 32704452, 2020). "CNTN1 expression was found to be elevated in thyroid tumor tissues in comparison to its pre-cancer counterparts, and this alteration was particularly evident in the junctional zones where normal glandular structure and tumorous structure meets." (PMID 32752094, 2020). "CNTN1 was consistently involved in cancer progression across different cancer types, but its role in cancer cell proliferation is contradictory." (PMID 33194679, 2020). "Further, an elevated expression of CNTN1 was found in HCC and was associated with cancer progression and poor prognosis." (PMID 33194679, 2020).
cancer (continued). "CNTN1 expression is upregulated at the transcriptional and translational levels in various cancer cell lines, cancer tissues, and transgenic mice." (PMID 33194679, 2020). "CNTN1 is a neuronal membrane glycoprotein, which, if overexpressed, is found in different cancer cell lines, cancer tissues, and transgenic mice." (PMID 33194679, 2020). "Like all successful molecular targeted therapy, an effective CNTN1-targeted therapy in cancer patients would benefit from a rational selection of delivery contexts." (PMID 32752094, 2020). "In accordance with the PRISMA guidelines, we performed a systemic literature search through the PubMed database using the term “Contactin 1” and “cancer”." (PMID 32752094, 2020). "Further, CNTN1 was found to be associated with the RhoA, Src-p38 MAPK-C/EBPα, Notch1, and RET/PTC3 pathways in cancers." (PMID 33194679, 2020). "The topic of CNTN1 in cancer progression has been previously reviewed, however some recent findings have been made and will be discussed." (PMID 32752094, 2020). "Clinical and experimental studies positively correlated the overexpression of CNTN1 with cancer progression and a poor prognosis." (PMID 33194679, 2020). "This review analyzes the up-to-date knowledge supporting CNTN1′s involvement in cancer progression and metastasis, and its related molecular mechanisms." (PMID 32752094, 2020). "In this paper, we will review CNTN1′s alterations in cancer, its main biochemical mechanisms and interactions with its relevant cancer pathways." (PMID 32752094, 2020). "Accumulating evidence from recent years suggest Contactin 1 (CNTN1)’s possession of multiple oncogenic activities in a variety of cancer types." (PMID 32752094, 2020). "Changes in the intercellular adhesive properties of cancer cells as a consequence of altered CNTN1 expression certainly play a role in tumorigenesis." (PMID 32752094, 2020). "In these subsections below, we will discuss in details current studies that have investigated CNTN1′s role in human cancers." (PMID 32752094, 2020). "Further, CNTN1 also correlates with cancer invasion, migration, and metastasis, especially to the lymph nodes." (PMID 33194679, 2020). "It is thus intriguing to envisage the possibility of immunotargeting of CNTN1 with a concurrent inhibition of cancer cell adhesion." (PMID 32752094, 2020). "Intriguingly, integrin α5 subunit function in the cellular signaling emanated from adhesion, supporting the involvement of the CNTN1 genes residing in this region in cancer adhesion." (PMID 32752094, 2020). "This review aims to summarize the research developments on CNTN1 in various cancers, to establish its role in epithelial-mesenchymal transition and signal transduction pathways, and to identify promising areas for further investigation." (PMID 33194679, 2020). "CNTN1 is a cell adhesion molecule that is dysregulated in many human carcinomas and plays important roles in cancer progression and metastases." (PMID 32752094, 2020). "Accumulating evidence has revealed that CNTN-1 is involved in carcinogenesis and cancer progression." (PMID 31427725, 2019). "In line with previous investigations, we observed that expression of CNTN-1 in resistant cells was higher than in progenitor cells, suggesting cancer stem cell-like characteristics with higher migration ability and anoikis resistance." (PMID 31427725, 2019). "Previously, the small GTP-binding protein RhoA has been demonstrated to be involved in Cntn1-induced F-actin polymerization during cancer cell migration." (PMID 30515076, 2018). "CNTN1, a DLX4 isoform, has been implicated in cell differentiation and early development, and its expression is frequently dysregulated in cancer." (PMID 29673312, 2018). "The VEGF-C/VEGFR-3 mediated invasion and metastasis of cancer cells were found to require upregulation of CNTN-1 through activation of the Src/p38 MAPK-mediated C/EBP signaling pathway." (PMID 23606831, 2013).
cancer (continued). "Reduction of contactin-1 resulted in upregulation of E-cadherin, consistent with E-cadherin being inhibitive of cancer cell invasion." (PMID 23724143, 2013). "Only recently have there been reports of CNTN-1 expression in diseases outside of the nervous system, most notably with its involvement in cancer." (PMID 23724143, 2013). "For example, it has been shown that VEGF or VEGF-C promoted cancer cell metastasis by up-regulation of integrin αvβ6 expression or of the neural cell adhesion molecule contactin-1 through divergent cellular signalings." (PMID 20429915, 2010). "Both PENK and CNTN1 have been detected in the prostate in other studies, and cancer down-regulation of PENK was evident in published datasets." (PMID 19737398, 2009). "Additionally, CNTN-1 was also reported to promote the malignant progression of cancer cells as a downstream molecule of the VEGF-C/Flt-4 axis." (PMID 35711928, 2022). "Recent reports have revealed that CNTN1 is also involved in carcinogenesis and cancer progression." (PMID 35171955, 2022). "Despite a complex relationship between CNTN1 and the LE genes, our analyses nonetheless clearly reveal the novel and robust prognostic biomarker potentials of LE genes not only in PC but also in other cancer types." (PMID 33578925, 2021). "In the last decade, contactin 1 (CNTN1) has surfaced as an important cancer-related molecule." (PMID 33194679, 2020). "Several studies suggest CNTN1 as a new therapeutic target for cancers." (PMID 33194679, 2020). "However, treatment with anti-CNTN1 antibodies inhibited cell invasion by 70%–80%, suggesting a critical role of CNTN1 in mediating cancer invasion induced by NNK." (PMID 33194679, 2020). "Those of interaction proteins in neuron development may shed light on the mechanisms responsible CNTN1-derived modulation of cancer adhesion." (PMID 32752094, 2020). "In view of the critical aspect of communications between cancer and stroma, proper adhesion is critical for cancer evolution or progression, targeting CNTN1 might thus be a useful option." (PMID 32752094, 2020). "In the last decade, CNTN1 has emerged as a promising oncogene in multiple cancer types." (PMID 32752094, 2020). "However, recent studies associate CNTN1 with EMT and several signal transduction pathways in numerous cancers." (PMID 33194679, 2020). "Therefore, in-depth investigations of molecular mechanisms are required to ascertain the role of CNTN1 in cancer cell proliferation." (PMID 33194679, 2020). "In addition, CNTN1 is involved in cancer cell invasion, migration, metastasis, and chemoresistance by promoting epithelial-mesenchymal transition and mediating several signal transduction pathways." (PMID 33194679, 2020). "This suggests that antibody-mediated immunotherapy toward CNTN1 may be a novel direction in cancer treatment." (PMID 33194679, 2020). "However, its oncogenic potential has not been thoroughly investigated, which limits our recognition of CNTN1′s utility in cancer diagnosis and therapy." (PMID 32752094, 2020). "Correlations between CNTN1 and other molecules in different cancers." (PMID 33194679, 2020). "By taking advantage of the recently established GEPIA2 program with RNA sequencing data from The Cancer Genome Atlas (TCGA) and Genotype-Tissue Expression (GTEx) projects, we performed survival analyses with respect to CNTN1 expression across all 33 TCGA cancer types." (PMID 32752094, 2020). "However, knockdown of CNTN1 in cancer cells led to a significant reduction in CNTN1, Slug, and N-cadherin expression as well as E-cadherin upregulation." (PMID 33194679, 2020). "Furthermore, knockdown of CNTN1 attenuated cancer progression and significantly increased drug sensitivity and cisplatin-induced apoptosis in both cisplatin-resistant cancer cells and the control." (PMID 33194679, 2020). "Thus, based on recent studies, CNTN1 is identified as a predictive biomarker and therapeutic target in several cancer types." (PMID 33194679, 2020).
cancer (continued). "On these premises, the interest of CNTN1 as a target to impede cancer progression is increasing." (PMID 32752094, 2020). "Likely, mechanisms leading to CNTN1 upregulation in cancers are complex." (PMID 32752094, 2020). "This precise mediation of gene expression may allow a more informative investigation in the functionality of CNTN1 in carcinomas." (PMID 32752094, 2020). "Furthermore, VEGF-C/Flt-4-mediated invasion and metastasis of cancer cells were found to be through the upregulation of the neural cell adhesion molecule CNTN1 which activated the Src-p38 MAPK-C/EBP-dependent pathway." (PMID 22580838, 2012). "In view of its malignant phenotype-promoting activities in cancer cells and its growth-promoting abilities in neural cells, this study investigated the possibility of CNTN1 as a prognostic marker for patients with OSCC and the association between CNTN1 expression and metastasis of OSCC in vivo." (PMID 22580838, 2012). "Thus, CNTN1 is a promising candidate for cancer-targeted therapy." (PMID 33194679, 2020). "Therefore, CNTN-1 is a promising potential target for cancer therapy." (PMID 31427725, 2019). "For another example, a neural cell adhesion protein CNTN1, mutated in 8.57% of the reclassified metastatic samples but in none of the reclassified metastatic samples, could promote cancer cell invasion and metastasis." (PMID 28922552, 2017). "Considering the particularity of OSCC in epidemiology, which is notably different from other cancer types, as well as the different molecule signatures in invasion and metastasis, in this study, we investigated whether CNTN1 is a major factor promoting OSCC progression and metastasis." (PMID 22580838, 2012). "Knocking down CNTN-1 partially reversed the epithelial-mesenchymal transition (EMT), improved drug sensitivity, and slowed the progression of cancer." (PMID 34659414, 2021). "The OSCC cells with CNTN1 knocked-down exhibits significant reduction in invasion but not proliferative properties, which is in line with previous findings demonstrating that CNTN1 may promote progression of cancer cells through exclusive activation of metastatic pathways." (PMID 32752094, 2020). "Further, CNTN1-induced EMT is mediated by the transcription factor Slug but not Snail, suggesting a specific mechanism involving CNTN1 in cancers." (PMID 33194679, 2020). "However, the role of CNTN1 in cancer cell proliferation remains unclear." (PMID 33194679, 2020). "CNTN1 inhibition also increased expression of E-cadherin while reduced N-cadherin and Vimentin, suggesting an inhibition of the EMT process pivotal in cancer metastases." (PMID 32752094, 2020). "Seven of these predicted proteins (NCAM1, CNTN1, SCG2, CADM1, IL-8, NPTX1, and APOD) were identified in five databases (SignalP 4.1, SecretomeP 2.0, Vesiclepedia, Human Cancer Secretome, and Plasma Proteome), giving support to their relevance in NSCLC." (PMID 31455042, 2019). "For example, re-expression of CNTN1, ITGA5, and CDH23 increased the numbers of colonies in the enhancer KO cells, affecting important properties of cancer cell growth." (PMID 31328168, 2019). "Recently, CNTN1 has been reported to mediate cell functions involving multiple signaling pathways, including the Notch signaling pathway, RHOA dependent pathway, RET/PTC3 pathway, and VEGFC/FLT4 axis to promote the invasion and metastasis of cancer cells." (PMID 38562021, 2024). "The involvement of CNTN1 in promoting EMT and AKT suggest a potential involvement in its facilitation of cancer stem cell-like characteristics such as migration and anoikis resistance in cancer cells." (PMID 32752094, 2020). "CNTN1 expression was significantly higher in different cancer tissues than in noncancerous controls." (PMID 33194679, 2020). "Despite the wide variety of cancers examined, CNTN-1 is not a universally expressed protein in cancer." (PMID 23724143, 2013).
cancer (continued). "Moreover, CNTN1 was identified as a direct downstream molecule of the vascular endothelial growth factor C (VEGFC)-VEGF receptor 3 (VEFGR3)/fms-related tyrosine kinase 4 (Flt4) axis important in lymphangiogenesis and lymphatic invasion in cancers." (PMID 32752094, 2020). "Moreover, after inhibiting AKT activation, the knockdown of CNTN1 failed to further reduce the invasive ability of cancer cells." (PMID 33194679, 2020). "Importantly, approximately 61% of CNTN-1 positive carcinomas are also E-cadherin-negative." (PMID 23724143, 2013). "However, we did observe carcinomas that were negative for both CNTN-1 and E-cadherin (data not shown), suggesting that CNTN-1 is not the only factor inhibiting E-cadherin expression." (PMID 23724143, 2013).
infection (7 papers, 2022 to 2026). The state of being infected such as from the introduction of a foreign agent such as serum, vaccine, antigenic substance or organism. "ACE2 expression made the cells susceptible to infection, as expected, whereas CNTN1 expression by itself promoted low to negligible levels of infection." (PMID 35931765, 2022). "The present study discovered that CNTN1 is downregulated upon infection with H1N1, H5N6, or H7N9 IAV subtypes." (PMID 35171955, 2022). "Remarkably, CNTN1 co-expression with ACE2 significantly increased pseudotyped particle infection relative to cells expressing ACE2 alone." (PMID 35931765, 2022). "In this study, using transcriptome deep-sequencing and data analysis, we discovered that host factor contactin-1 (CNTN1) expression was reduced upon infection with various subtypes of IAV." (PMID 35171955, 2022). "Surprisingly, using spike pseudotyped particles as a surrogate to study viral entry, we show that CNTN1 enhances ACE2-dependent infection." (PMID 35931765, 2022). "For example, FOXO1 and CNTN1 levels temporarily dropped during infection." (PMID 40760251, 2025). "Alternatively, or in addition, CNTN1 could mediate ACE2-independent routes of infection in vivo in inflamed tissues with high viral load." (PMID 35931765, 2022). "Furthermore, CNTN1 expression also increased infection in the presence of ACE2 and TMPRSS2, relative to ACE2 and TMPRSS2 alone." (PMID 35931765, 2022). "Furthermore, CNTN1 levels were observably decreased in A549 cells following infection with H1N1 or H7N9 viruses." (PMID 35171955, 2022). "Low-titer anti-neurofascin-155, but no anti-contactin-1 autoantibodies, were detected in 1/280 post-SARS-CoV-2-vaccination or infection sera (0.36%)." (PMID 41906364, 2026).
peripheral neuropathy (6 papers, 2018 to 2024). A disorder affecting the peripheral nervous system. "Recent studies provide insight into the pathogenic mechanisms of CNTN1 antibody-mediated peripheral neuropathy." (PMID 36893151, 2023). "Antibodies to neurofascin 155 are thought to have a similar effect to antibodies against CNTN1, with a block of CNTN1/Caspr1–neurofascin 155 interaction affecting paranodal structure and causing peripheral neuropathies." (PMID 29483905, 2018).
neurological disorders (4 papers, 2020 to 2026). "Emerging data also reveals the presence of CNTN1 protein in serum, and show levels reflect antibody status and neurological disease activity." (PMID 36893151, 2023). "Finally, using western blotting we observed CNTN1 within the PEG precipitates isolated from the serum of a patient with active renal and neurological disease (patient 14 in S1 Table in S1 File)." (PMID 36893151, 2023).